KRAS (KRas proto-oncogene, GTPase)
Diseases named in the same sentence as KRAS in open-access papers (continued):
Sharing a sentence is not in itself a finding about the gene and the disease.
cancer (continued). "In 2013, the National Center Institute (NCI) established “The RAS initiative” to mobilize the community involved in the research of cancers driven by the RAS gene family (KRAS, HRAS and NRAS)." (PMID 39457457, 2024). "In HDAC5-rich tumors, these macrophages increase TGFβ production, triggering pSMAD3/SMAD4 signaling in cancer cells, and bypassing the need for KRAS." (PMID 38668053, 2024). "Our results provide a strategy for treating KRAS-mutant cancers through personalized selection based on MYC expression." (PMID 38992694, 2024). "Adoptive T-cell therapy has emerged as a promising approach for the treatment of KRAS-mutant cancers." (PMID 38668053, 2024). "The paradigm from considering KRAS as undruggable to the development of KRAS inhibitors represents a significant paradigm shift in cancer therapeutics and a promising strategy in CRC." (PMID 39456549, 2024). "Activating the P21 protein through editing the KRAS gene can sensitize cancer cells to chemotherapy." (PMID 38195537, 2024). "Our multiplexed testing results and in vivo examination of ctDNA from animal models of human KRAS-driven cancers support the capability of PROMER technology." (PMID 38938409, 2024). "Consistent with RMC-6236 sensitivity and KRAS dependency in human cancer cells in vitro, RMC-6236 monotherapy drove durable antitumor activity and frequent regressions in KRASG12X xenograft models across all indications tested." (PMID 38593348, 2024). "In conclusion, while significant strides have been made in the understanding and treatment of KRAS-mutant cancers, the journey towards optimal therapeutic strategies is far from complete." (PMID 39252322, 2024). "For example, a study identified a novel KRAS Y96D mutation that interferes with protein-drug interactions in the switch-II pocket and confers resistance to inhibitors in a KRAS G12C cancer model." (PMID 38655260, 2024). "The prevalence of RAS mutations in human cancer has long been recognized, with KRAS being the most frequently mutated gene, accounting for 85% of all RAS-driven cancers." (PMID 39149589, 2024). "We aim to delineate the role of STAT3 in shaping the patterns of oncogenic KRAS dependency in KRAS mutant cancer cells." (PMID 38573819, 2024). "Given the compensatory responses to CDK9i in KRAS‐mutant cancers, we further performed high‐throughput screening (HTS) using a custom library comprising ≈40 compounds to screen combinational strategies." (PMID 39254172, 2024). "Thus, co-inhibition of YAP–/TAZ–TEAD and KRAS G12C could be a promising combination for KRAS G12C-mutated advanced cancers when the safety and efficacy of YAP–/TAZ–TEAD inhibitors are established in ongoing early-phase clinical trials (NCT05228015, NCT04665206)." (PMID 38756650, 2024). "As part of a meticulous scientometric analysis, we identified journals that serve as major platforms for disseminating groundbreaking research in the field of KRAS-induced cancer immunotherapy." (PMID 39252322, 2024). "Collectively, these data indicate that ARS-1620 enhances GLI-1 binding to the KRAS promoter in cancer cells." (PMID 38225225, 2024). "Cancer cell metabolism is critical to survival and in PDAC, KRAS mutations shape a unique metabolic environment which drives aerobic glycolysis." (PMID 38576709, 2024). "Notwithstanding the attractiveness of KRAS as an anti-cancer drug target, it was thought by many to be “undruggable” after multiple biopharmaceutical companies tried and failed." (PMID 38886570, 2024). "Immunofluorescence staining with human-specific antibody STEM121 and mCherry (expressed on the same cassette as oncogenic KRAS) confirmed the human origin of the cancer lesions." (PMID 38280869, 2024). "An array of cancers harboring oncogenic alterations of PIK3CA, KRAS, PTEN, EGFR, and RHOA have been reported to be associated with activated PI3K/AKT-mTOR signaling." (PMID 39164472, 2024).
cancer (continued). "This discovery gains significance considering the ability of KRAS G12D to boost GM-CSF production in PDAC cancer cells, thereby attracting immunosuppressive myeloid cells that can dampen the activity of CD8 T-cells." (PMID 38668053, 2024). "KRAS hyperactivity has recently been demonstrated to upregulate PDL-1 expression in cancer cells, rendering these malignancies resistant to T cell therapy." (PMID 38553450, 2024). "KRAS is an oncogene that encodes a small GTPase transductor protein called K-RAS, which is the most frequently mutated isoform in RAS-driven cancers (86%), followed by N-RAS (11%) and H-RAS (3%)." (PMID 38881031, 2024). "CNBP was shown to control transcription of c-MYC and KRAS oncogenes in human cancer by unfolding DNA G-quadruplex structures." (PMID 38635778, 2024). "Overall, a range of studies highlights the direct role of MYC in regulating multiple cell- autonomous tumorigenic mechanisms in KRAS-driven cancers, indicating potential vulnerabilities under its cooperation." (PMID 39164274, 2024). "The RAS genes which code for KRAS, HRAS, and NRAS are three of the most frequently mutated oncogenes responsible for cancer deaths." (PMID 39184150, 2024). "Although inhibiting downstream effectors like the MAPK and PI3K pathways has shown success in some cancer types, it falls short in KRAS mutant patients." (PMID 39164274, 2024). "Multiple studies have demonstrated the clinical potential of targeting downstream signaling to selectively intervene in KRAS-mutant cancer." (PMID 38473386, 2024). "Similar findings were reported in CRC and other cancer types, emphasizing the significant implications for developing KRAS inhibitors, particularly targeting G12C, G12D, and G12V mutations." (PMID 39273605, 2024). "This general resistance mechanism to multiple KRAS inhibitors sheds light on an opportunity to overcome resistance to KRAS inhibitors and improve outcomes for patients with KRAS-mutant cancers through modulation of the Hippo-YAP/TAZ pathway." (PMID 39704172, 2024). "The aberrant activation of the p44/42 MAPK pathway, also known as RAS-RAF-MEK-ERK signaling, in KRAS-driven cancers, has generated significant interest in targeting the downstream effectors of this cascade as a therapeutic approach." (PMID 38409090, 2024). "We reconfirmed the correlational analysis data with the expression of MAP1LC3B, ATG5, ATG13, and ATG14 in cancer patients, in KRAS-mut compared to KRAS-WT (p < 0.05)." (PMID 39057088, 2024). "Pathways downstream of KRAS ultimately promote proliferation and cell survival, which are key to the growth and maintenance of cancer cells when KRAS is inappropriately activated." (PMID 38668053, 2024). "This emphasizes the necessity for additional research into the complicated dynamics of KRAS targeting in cancer therapy." (PMID 39001451, 2024). "Next, we examined the efficacy of combination treatment with trametinib and TAK-981 in MYC-expressing KRAS-mutant cancer cells." (PMID 38992694, 2024). "When BSC was the control arm (the ‘later line’ trials), EGFR mAb therapy provided OS and PFS benefit in patients with KRAS WT cancers (OS HRadj 0.79, p = 0.036 and PFS HRadj 0.41, p < 0.001)." (PMID 38402342, 2024). "Top 10 most productive countries/regions in the research of KRAS-related cancer during 2013 to 2022." (PMID 38706597, 2024). "Considered as the holy grail of cancer drug discovery, because of its own characteristics, KRAS has been regarded as undruggable for years." (PMID 38261067, 2024). "Cancer effects for well-known, frequently mutated genes like NRAS and KRAS in B-ALL were high, which underscores their importance as therapeutic targets." (PMID 38928295, 2024). "Similar sustained pERK suppression and moderate PARP cleavage were also observed in two additional KRAS-mutant cancer cells." (PMID 38589574, 2024).
cancer (continued). "Although KRAS G12C inhibitors have proven that KRAS is a “druggable” target of cancer, KRAS G12C inhibitor monotherapies have demonstrated limited clinical efficacy due to primary and acquired resistance mechanisms." (PMID 38756650, 2024). "KRAS is the predominant isoform among RAS mutations, occurring frequently in various cancers, particularly CRC." (PMID 39657309, 2024). "These innovative therapies, now in various stages of development, show promising results by selectively inhibiting KRAS function in cancer cells." (PMID 39061234, 2024). "A possible link of KRAS c.34G>T mutation to LINE‐1 hypomethylation and early‐onset carcinoma should be investigated in future larger studies because the sample size of early‐onset carcinoma is limited in this study." (PMID 39039804, 2024). "For the two patients with cancerous progression, the first patient was diagnosed as TVA mixing with carcinoma at the initial time and contained somatic mutations including APC, KRAS, and ARID1A." (PMID 39554798, 2024). "Mutation analysis revealed that RAS mutations, including KRAS and NRAS, were only detected in the tissues of carcinomas." (PMID 39021676, 2024). "To explore how c-MYC mediates resistance to T/CQ, we examined the cell division cycle, one of the hallmarks of cancer modulated by activated KRAS and c-MYC." (PMID 36719686, 2023). "The immunosuppressive role of oncogenic KRAS is multifaceted, directly and indirectly affecting various steps of the cancer-immunity cycle." (PMID 37558751, 2023). "YAP was shown to function together with KRAS in cancer cells dependent on KRAS for viability to promote not only cell survival but also EMT." (PMID 37835395, 2023). "We are currently witnessing a large wave of next-generation drugs for KRAS mutant cancers—nucleic acid-based therapeutics." (PMID 38069255, 2023). "KRAS is a well-documented therapeutic target for cancer due to its widespread occurrence in a variety of life-threatening malignancies." (PMID 37822837, 2023). "The KRAS (Kirsten rat sarcoma viral oncogene) isoform represents 75% of RAS mutant cancers and is therefore considered a crucial oncogene." (PMID 37907934, 2023). "Of note, many of the studies mentioned in this section were conducted in non-cancer cell types, and the precise role of vimentin in regulating ferroptosis in KRAS-mutant cancer remains to be identified." (PMID 37161053, 2023). "PacDNA is a promising therapeutic platform for addressing KRAS-driven human cancers and warrants further exploration in both preclinical and clinical settings." (PMID 38069255, 2023). "Although targeting the lysosome is not a cancer-specific approach per se, we found that CSCs and KRAS-mutant cancer cells were more vulnerable to ARL-17477 than were other cancer cells." (PMID 37402770, 2023). "KRAS is expressed in both cancer and normal lung and liver tissues, and we found that the expression of KRAS mRNA in lung tissue is higher than that in liver tissue." (PMID 38206735, 2023). "Several in vitro studies have used CRISPR-based cleavage approaches to disrupt mutant KRAS, and have demonstrated the potential of this system for treating patients with KRAS mutant cancers." (PMID 38069255, 2023). "The proliferation of endothelium stem and progenitor cells is controlled by activated KRAS, which also plays a role in promoting the development of endodermally derived cancers." (PMID 36936437, 2023). "We have previously demonstrated that KRAS mutant glycolytic cancer cells challenged with 13C-glucose produce labeled MG and accumulate MG protein adducts." (PMID 37408249, 2023). "How KRAS mutant cancer cells manage to sustain such high levels of arachidonic acid to be able to sustain the prostaglandin production is not well understood." (PMID 36675307, 2023). "Activation of the KRAS oncogene is a source of replication stress, but how this stress is generated and how it is tolerated by cancer cells remain poorly understood." (PMID 37591859, 2023).
cancer (continued). "Oncogenic KRAS is responsible for cancer cell proliferation, energy metabolism, chemoresistance, invasion and metastasis." (PMID 36936437, 2023). "Research has shown that abnormal metabolism in cancer cells is related to abnormal expression of the proto-oncogenes cMyc, KRAS, and BRAF." (PMID 37394582, 2023). "The mechanisms underlying EGFR–TKI resistance in NSCLC can be broadly categorized into acquired resistance following EGFR–TKI treatment and primary resistance characterized by cancer cells relying on alternative oncogenes like KRAS." (PMID 37816585, 2023). "In terms of clinical application for KRAS mutant cancer, MEK inhibitors are observed to have little efficacy clinically, and MEK inhibitors for RAS mutant tumors per se have not yet been accepted into clinical trials." (PMID 36872366, 2023). "Although not statistically significant, potentially due to limited patient counts, patients with KRAS G12C–positive cancer treated with 1L CIT showed a trend toward longer survival vs patients with KRAS WT cancer." (PMID 37069542, 2023). "Their relationship has been demonstrated in the appearance of up to 25% of various types of human cancers, 85% of which correspond to genetic alterations present in KRAS." (PMID 37566020, 2023). "Using targeted sequencing data from MSK-IMPACT and DFCI-GENIE databases we identified co-mutations in HRAS- vs KRAS- and NRAS-mutant cancers." (PMID 37503077, 2023). "Considering the Afirma Gene Expression Classifier and ThyroSeq genomic classifier are not yet available in China and are expensive, 5 of the most common cancer-associated somatic mutations (BRAF, HRAS, NRAS, KRAS and TERT) were offered in our hospital." (PMID 36737779, 2023). "Mutations in the KRAS gene, and protein overexpression of c-MYC (referred to as MYC) and ARF6 are frequent in many types of cancers." (PMID 37158894, 2023). "Further steered-molecular dynamics, molecular-dynamics simulation, toxicity, and in silico cancer-cell-line cytotoxicity predictions significantly support these four lead bioflavonoids as potential inhibitors of KRAS G12D SI/SII inhibitors." (PMID 36975507, 2023). "We next investigated the S03 state of fibroblasts in detail and found that three cancer hallmark-related pathways were significantly enriched by marker genes, including MYC targets, KRAS signaling down and cytokines." (PMID 37500893, 2023). "Despite the novelty and significance of being able to directly target KRAS-G12C-mutant cancers, clinical trials of both Adagrasib and Sotorasib have shown acquired resistance." (PMID 37190303, 2023). "We used DEMETER2 as our KRAS cancer dependency dataset as it combined three large-scale RNAi screen datasets and integrated them with model-based normalization." (PMID 37141389, 2023). "Intriguingly, among the various KRAS mutants, p.G12D, which is the most prevalent in cancer, exhibits the closest resemblance to the wt in terms of its dynamics." (PMID 37509241, 2023). "Consistent with these efforts in KRAS-driven cancer, we evaluated SHP2 therapy in our previous study as an adjunct to MEK therapy in KRAS-amp GEA." (PMID 36752207, 2023). "KRAS-mutant cancer cell metabolism is followed by endoplasmic reticulum stress and proteotoxic activation of unfolded protein response (UPR) pathways, which result in cell death." (PMID 36899885, 2023). "It was revealed that in CRC tissues, miR-30b inhibited cancer cells cycle progression and the expression of miR-30b was negatively correlated with the KRAS expression." (PMID 36639711, 2023).
cancer (continued). "Vaccines, including mRNA-based vaccines, provide a new opportunity for the treatment of KRAS mutant cancers." (PMID 38069255, 2023). "For example, the occurrence of KRAS alterations in the current study (49.5%) was higher than that reported at cBioPortal, a resource hosting genomic data from large cancer sequencing consortiums and individual studies (44.7%)." (PMID 36902296, 2023). "Further investigation suggests that lysosomal activity is essential for KRAS-driven cancer growth, but avicin G inhibits this by enhancing lysosomal PH and preventing phosphorylation of ERK signaling." (PMID 36975494, 2023). "The AML had overall gained 4 mutations in cancer genes: ETV1 (p.R405H, VAF 30.4%), KRAS (p.G12A, VAF 27.9%), PARP1 (c.2277 + 1G > C, VAF 7.5%), and ETV6 (p.I358M, VAF 5.3%)." (PMID 38012682, 2023). "Targeting KRAS in cancer has been a central goal during the past four decades, but it is not until recently that all these efforts have started to bear fruit." (PMID 36614192, 2023). "Another study found that inhibition of nuclear trafficking via XPO1 leads to a synthetic lethal effect on KRAS-mutant cancer cells through the inhibition of transcription factor NF-κB, introducing a targetable notion for NSCLC therapies." (PMID 36899885, 2023). "KRAS-mutant cancer cells can produce exosomes that are enriched in Survivin, to promote cancer cell survival and resistance to therapy." (PMID 36675641, 2023). "Our study suggests that most KRAS oncoproteins cycle between an active state and an inactive state in cancer cells and are dependent on nucleotide exchange for activation." (PMID 37258666, 2023). "The studies indicated that the presence of mutations in almost all major cancers makes RAS proteins a significant therapeutic target, in particular for KRAS, because it was recognized as one of the most frequently mutated oncogenes." (PMID 37049650, 2023). "The role of KRAS in cancer progression is well-studied, but until recently the protein has largely been considered “undruggable”." (PMID 37141389, 2023). "Mutant KRAS plays a crucial role in proliferation and survival in several cancers, and G12, G13, and Q61 are the hotspot residues, with mutational frequencies of 83%, 14%, and 2%, respectively." (PMID 36975507, 2023). "STK11 WT-mKEAP1 and STK11 WT-KEAP1 WT were more prevalent in patients with KRAS WT cancer, than those with KRAS G12C-positive cancer (15.0% vs 8.1%; p = 0.01 and 65.9% vs 53.4%, p = 0.02, respectively)." (PMID 37069542, 2023). "The ability of the KRASi to suppress MAPK output more potently in KRAS mutant models correlated, on average, with a more potent antiproliferative effect in a panel of 274 cancer cell lines." (PMID 37258666, 2023). "Our findings identify RASON as a critical regulator of oncogenic KRAS signaling and a promising therapeutic target for KRAS mutant cancers." (PMID 36241718, 2023). "In contrast, overexpression of β3 in the null cell line H727 promoted the growth of cancer cells, which were perturbed by shRNA KRAS or galectin-3 knockdown." (PMID 37371482, 2023). "KRAS was the first oncogene identified in human cancer and activating mutations affecting members of the RAS family genes (KRAS, HRAS, NRAS) are the most frequent genetic alterations, being found in about 27% of all tumors." (PMID 36614192, 2023). "They reported that PDK4 knockdown by specific small interfering (si)RNAs downregulates mutant (KRAS) expression and consequently strongly suppresses the growth of cancer cells." (PMID 36835086, 2023).